LIN7B (lin-7 cell polarity scaffold B)
Description:
Plays a role in establishing and maintaining the asymmetric distribution of channels and receptors at the plasma membrane of polarized cells. Forms membrane-associated multiprotein complexes that may regulate delivery and recycling of proteins to the correct membrane domains. The tripartite complex composed of LIN7 (LIN7A, LIN7B or LIN7C), CASK and APBA1 associates with the motor protein KIF17 to transport vesicles containing N-methyl-D-aspartate (NMDA) receptor subunit NR2B along microtubules (By similarity). This complex may have the potential to couple synaptic vesicle exocytosis to cell adhesion in brain. Ensures the proper localization of GRIN2B (subunit 2B of the NMDA receptor) to neuronal postsynaptic density and may function in localizing synaptic vesicles at synapses where it is recruited by beta-catenin and cadherin. Required to localize Kir2 channels, GABA transporter (SLC6A12) and EGFR/ERBB1, ERBB2, ERBB3 and ERBB4 to the basolateral membrane of epithelial cells. May increase the amplitude of ASIC3 acid-evoked currents by stabilizing the channel at the cell surface (By similarity).
Synonyms: Lin-7B; MALS-2; MALS2; VELI2
Tractability: Antibody: UniProt places it where antibodies can reach, with high confidence; its Gene Ontology location is reachable by antibodies, with high confidence.
Gene: Protein-coding gene on chromosome 19 (49,114,324 to 49,118,460, forward strand). Ensembl gene ENSG00000104863.
Subcellular location: Cell membrane; Basolateral cell membrane; Cell junction; Postsynaptic density membrane; Cell junction, tight junction
Pathways (Reactome):
Neuronal System: Assembly and cell surface presentation of NMDA receptors; Dopamine Neurotransmitter Release Cycle; Neurexins and neuroligins
Signal Transduction: RHO GTPases Activate Rhotekin and Rhophilins
Gene Ontology:
Molecular function: protein binding; protein domain specific binding; protein-macromolecule adaptor activity
Biological process: neurotransmitter secretion; protein transport; regulation of synaptic assembly at neuromuscular junction; synaptic vesicle transport
Cellular component: basolateral plasma membrane; anchoring junction; cell-cell junction; membrane; MPP7-DLG1-LIN7 complex; plasma membrane; postsynaptic density membrane; synapse; bicellular tight junction; presynapse
Genetic constraint (gnomAD): Loss-of-function variants: 14 observed, 19.06 expected, observed/expected ratio (o/e) 0.73, 90% interval 0.48 to 1.15. The synonymous counts are far from expectation, so gnomAD's model fits this gene poorly and the ratio says little. Missense variants: 260 observed, 242.68 expected, observed/expected ratio (o/e) 1.07, 90% interval 0.97 to 1.19. Synonymous variants: 130 observed, 100.09 expected, observed/expected ratio (o/e) 1.3, 90% interval 1.13 to 1.5.
Homologues: Orthologues: chimpanzee LIN7B (100% identical), guinea pig LIN7B (100% identical), macaque LIN7B (100% identical), rat Lin7b (99% identical), mouse Lin7b (98% identical), pig LIN7B (95% identical), tropical clawed frog lin7b (93% identical), zebrafish lin7b (90% identical), dog LIN7B (81% identical), Drosophila melanogaster veli (73% identical), Caenorhabditis elegans lin-7 (64% identical). Paralogues in human: LIN7C (80% identical), LIN7A (75% identical), PDZD11 (26% identical).
Diseases named in the same sentence as LIN7B in open-access papers:
LIN7B is named in the same sentence as 1 disease in open-access papers, as found by Europe PMC text mining. Sharing a sentence is not in itself a finding about the gene and the disease. The quoted sentences say what the papers report.
schizophrenia (3 papers, 2008 to 2024). A major psychotic disorder characterized by abnormalities in the perception or expression of reality. "LIN7B encodes a protein involved in protein binding and maintaining distribution of channels and receptors in the cell membrane and is involved in neurotransmitter secretion with previous association with schizophrenia." (PMID 25147559, 2014). "When we compared the full set of female and male schizophrenia DEGs across brain regions, we found an additional three overlapping genes (CD99, GABARAPL1, and LIN7B) shared with the caudate nucleus." (PMID 38730231, 2024). "Phosphoinositide-3-kinse regulatory subunit polypeptide 1 (PIK3R1), AT-binding transcription factor 1 (ATBF1), Lin-7 homolog b (Lin-7b) and calcium-independent phospholipase A2 gamma (IPLA2γ), had significantly altered expression in the STG in schizophrenia identified by microarray analysis." (PMID 18445270, 2008).